BDNF (brain derived neurotrophic factor)
Diseases named in the same sentence as BDNF in open-access papers (continued):
Sharing a sentence is not in itself a finding about the gene and the disease.
fibromyalgia (continued). "It was assessed the pain score on the Visual Analog Scale (VAS 0-100 mm), the score on Fibromyalgia Impact Questionnaire (FIQ), heat pain threshold (HPT), sleep quality and BDNF serum." (PMID 25052847, 2014). "A lower concentration of serum brain-derived neurotrophic factor was reported in patients with fibromyalgia, but a difference between NcplP and nociceptive pain was not significant." (PMID 37372912, 2023). "Also, we evaluated the relationship between the BDNF Val66Met genotype with the DPMS and the impact of symptoms on quality of life due to fibromyalgia (secondary outcomes)." (PMID 36336706, 2022). "The primary objective was to compare the serum brain-derived neurotrophic factor (BDNF) level in the patients with two types of pain: fibromyalgia (FM) and non-FM nociceptive pain (non-FM NP)." (PMID 35501732, 2022). "Our study fails to replicate the finding that peripheral BDNF is altered in fibromyalgia, and instead our findings suggest that plasma levels of growth factor appear normative in fibromyalgia." (PMID 31541132, 2019). "We hypothesized increased levels of BDNF and NGF in fibromyalgia patients as compared to pain-free controls, indicative of peripheral sensitization in the chronic pain population." (PMID 31541132, 2019). "Contrary to the study hypotheses, fibromyalgia patients were indistinguishable from pain-free controls on both plasma NGF and BDNF levels." (PMID 31541132, 2019). "The most marked study limitation is that no cerebrospinal fluid measures of BDNF and NGF were taken, and thus no conclusions can be drawn as to whether central growth factor levels are altered in fibromyalgia." (PMID 31541132, 2019).
hippocampal atrophy (49 papers, 2012 to 2025). "This hippocampal atrophy was reported to be accompanied by the inhibition of neurogenesis caused by decreased production of BDNF." (PMID 33790733, 2021). "In the present cross-sectional study, logistic regression analysis revealed that age, sport activity, hippocampal atrophy, and BDNF were independently associated with memory function determined by RBMT." (PMID 33020545, 2020). "Many studies have demonstrated that chronic stress causes hippocampal atrophy, reduces neurotrophin levels, such as brain-derived neurotrophic factor (BDNF), and decreases neurogenesis." (PMID 30149419, 2018). "Notwithstanding this limitation, results of the current study provide preliminary support for high Aβ and BDNF Val66Met polymorphism as important prognostic markers of increased memory decline and hippocampal atrophy in individuals with prodromal AD." (PMID 24475133, 2014). "However, previous longitudinal reports on amyloid-positive CU individuals have described that the BDNF Val66Met allele was associated with a steeper decline in cognitive function and hippocampal atrophy." (PMID 32804326, 2020). "In addition, it has been suggested that the BDNF Val66Met polymorphism moderates the memory decline and hippocampal atrophy in prodromal AD subjects with high baseline levels of Aβ." (PMID 29896439, 2018). "While increased memory decline and hippocampal atrophy have been reported previously in adults with aMCI and high Aβ [10−12], results of the current study suggests a direct link between Aβ and the BDNF Val66Met polymorphism on progressive memory decline and hippocampal atrophy in prodromal AD." (PMID 24475133, 2014). "The first hypothesis that the BDNF Val66Met polymorphism would moderate memory decline and hippocampal atrophy in aMCI with high Aβ was supported." (PMID 24475133, 2014). "Recently, we observed an epistatic relationship between the BDNF Val66Met polymorphism and Aβ deposition in which BDNFMet healthy individuals showed a faster rate of hippocampal atrophy and episodic memory decline than BDNFVal homozygotes, but only if they had abnormally high Aβ." (PMID 24475133, 2014). "Gait slowness related to inactivity may cause hippocampal atrophy by decreased level of BDNF." (PMID 35915130, 2022). "Moreover, a recent study in the Australian Imaging, Biomarkers and Lifestyle study found that healthy adults with high Aβ levels who also had a Met allele of BDNF rs6265 had significant declines in episodic memory, executive function, and greater hippocampal atrophy over 3 years." (PMID 24086677, 2013). "For example, in the case of AD, noticeably low plasma BDNF can occur up to 10 years before the onset of clinical symptoms and correlates with hippocampal atrophy, as observed in standard structural MRI imaging." (PMID 40362507, 2025). "Physical exercise, especially aerobic, improves cognitive function and memory while attenuating hippocampal atrophy in older adults, with BDNF playing a key role." (PMID 39935805, 2024). "The low levels of the brain-derived neurotrophic factor (BDNF) induced by higher sugar consumption, which has been discussed as facilitating neurogenesis and hippocampal atrophy in depressive symptoms." (PMID 37340419, 2023). "Taken together, our results have suggested the involvement of AMPK/PGC-1α/BDNF signalling in the action of AdipoRon on rescuing hippocampal atrophy in diabetic mice." (PMID 34164760, 2021). "We investigated the relationship between cognitive function tests, hippocampal atrophy, sport activity, and the log10 BDNF value, using a graphical multivariate analysis SEM." (PMID 33020545, 2020). "Many environmental and hormonal factors such as physical exercise, caloric restriction, estrogen levels, and environmental enrichment can influence BDNF levels, making it challenging to link BDNF to age-related memory impairment and hippocampal atrophy." (PMID 31440144, 2019).
hippocampal atrophy (continued). "In particular, recombinant BDNF was able to ameliorate neuropathological features by significantly reduce both hippocampal atrophy and the number of NIIs in all hippocampal subfields." (PMID 30881980, 2019). "Comparing to Val/Val homozygotes, significantly higher rates of hippocampal atrophy and accelerated episodic memory decline were observed in BDNF Met carriers with amnestic mild cognitive impairment (aMCI) and high Aβ density." (PMID 29896439, 2018). "Thus, while high baseline Aβ was associated with memory decline and hippocampal atrophy, the deleterious effects were reduced in individuals who carried the BDNF Val66Met polymorphism that has been associated with greater secretion of the BDNF protein (i.e., BDNFVal homozygotes)." (PMID 24475133, 2014). "In addition, insulin prevents hippocampal atrophy neuronal loss, increasing neuronal density, doublecortin, PSD95 and BDNF levels." (PMID 41146261, 2025). "BDNF plays a significant role in cognitive health, with its signaling pathway contributing to reduced apoptosis in hippocampal neurons and protection against hippocampal atrophy, a key feature of CI." (PMID 40726602, 2025). "These include alterations in the monoaminergic system, changes in glutamatergic synaptic transmission, neuro-inflammation, alterations in the hypothalamic-pituitary-adrenocortical (HPA) axis, changes in brain-derived neurotrophic factor (BDNF), and hippocampal atrophy." (PMID 39703925, 2024). "Furthermore, depressed patients exhibit abnormally low levels of brain-derived neurotrophic factor (BDNF), a crucial regulator of neurogenesis and neuronal plasticity, contributing to hippocampal atrophy and neuronal loss." (PMID 39796528, 2024). "Moreover, BDNF is involved in long-term potentiation (LTP) in the hippocampus, and the decreased expression of BDNF contributes to hippocampal atrophy and neuronal loss in experimental animals." (PMID 35628418, 2022). "Moreover, chronic stress induces hippocampal atrophy and reduces the BDNF gene expression in limbic structures that take part in mood regulation, including the hippocampus and prefrontal cortex." (PMID 34610834, 2021). "Exercise may have a preventive effect due to the neurotrophic factor (BDNF) secreted by the brain, which can prevent hippocampal atrophy and maintain cognitive function." (PMID 34948942, 2021). "Furthermore, decreased serum levels of irisin, a potent inducer of BDNF, is associated with increased mood disturbances in COPD and hippocampal atrophy has been identified in COPD." (PMID 34743729, 2021). "Path analysis based on SEM indicated that the direct paths from age (β = 0.290, p < 0.001), sport (β = 0.186, p = 0.001), hippocampal atrophy (ZAdvance) (β = 0.142, p = 0.019), and log10 BDNF (β = 0.138, p = 0.015) to memory dysfunction (Rivermead) were significant." (PMID 33020545, 2020). "Also, transgenic overexpression of the neurotrophin BDNF has antidepressant effects and prevents chronic stress-induced hippocampal atrophy in mice." (PMID 22272355, 2012). "This is an interesting topic, and this combined modality within the context of serum BDNF levels and the analysis of CSF, markers of neuroimaging (e.g., hippocampal atrophy), and genetic profiling may increase detection of disease in early stages and monitoring of therapeutic efficacy." (PMID 40362507, 2025). "Moreover, human carriers of the BDNF Val66Met polymorphism, which ultimately results in decreased levels of secreted BDNF, have shown increased rates of decline in memory and hippocampal atrophy relative to Val66Val carriers in the preclinical and prodromal stages of sporadic AD." (PMID 34440640, 2021). "One study demonstrated that healthy adult BDNF Val66Met carriers with high amyloid burden showed significant and moderate to large declines in episodic memory, executive function, and language, and greater hippocampal atrophy after 36 months, compared to Val/Val homozygotes." (PMID 34440640, 2021).
hippocampal atrophy (continued). "Therefore, we speculated that PAPZ may promote neurogenesis or change neuroplasticity by increasing the level of BDNF protein, and thus play an antidepressant role in reversing hippocampal atrophy and cell damage." (PMID 30995790, 2019). "Thus, the reduction in BDNF may also contribute to hippocampal atrophy in PD patients." (PMID 38421103, 2024). "Our previous studies have shown that HDACi protects against CCH‐induced hippocampal atrophy, prevents cognitive dysfunction and affects the acetylation status of H3K14 and H4K5, thereby increasing the expression of different BDNF isoforms." (PMID 34216182, 2021). "The RBMT score was negatively correlated with hippocampal atrophy (i.e., higher ZAdvance score) (Pearson correlation coefficient r = 0.380, p < 0.001), while the RBMT score was positively correlated with BDNF (r = 0.203, p = 0.001)." (PMID 33020545, 2020). "Firstly, low levels of the growth factor brain derived neurotrophic factor (BDNF) have been discussed as facilitating neurogenesis and hippocampal atrophy in depression." (PMID 28751637, 2017). "Path analysis based on SEM indicated that age, sport activity, hippocampal atrophy and BDNF but not proBDNF were individually associated with RBMT." (PMID 33020545, 2020). "Path analysis based on structural equation modeling indicated that age, sport activity, hippocampal atrophy and BDNF but not proBDNF were individually associated with Rivermead Behavioral Memory Test scores." (PMID 33020545, 2020). "Although the direct path from age to executive dysfunction (Stroop) were significant (β = − 0.426, p < 0.001), the direct paths from log10 BDNF to hippocampal atrophy and executive dysfunction were not significant." (PMID 33020545, 2020). "This is in accordance with the neurotoxicity hypothesis of hippocampal atrophy in MDD, explaining hippocampal volume reduction by prolonged exposure to stress-induced biochemical abnormalities, mediated e.g. via HPA-axis, BDNF, or inflammatory processes." (PMID 25051163, 2014). "We found that there was a significant relationship between the BDNF Val66Met (rs6265) SNP and percent of right hippocampal atrophy over two years in nondemented individuals." (PMID 24086677, 2013). "The brain-derived neurotrophic factor (BDNF) protein helps support the growth, function, and survival of neurons in the brain and is heavily involved in neuroplasticity processes and synaptogenesis; reduced BDNF levels have also been correlated with hippocampal atrophy." (PMID 40453264, 2025).
eating disorder (48 papers, 2008 to 2025). A broad group of psychological disorders with abnormal eating behaviors leading to physiological effects from overeating or insufficient food intake. "Other BDNF haplotypes have been implicated in AN and related eating disorders, such as bulimia nervosa." (PMID 39203753, 2024). "Some common single-nucleotide polymorphisms of the brain-derived neurotrophic factor (BDNF) gene have been associated not only with the neurodegenerative diseases but also with some eating disorders." (PMID 37085692, 2023). "The study on eating disorders found a significant association between the BDNF C270T polymorphism and low BMI in individuals with bulimia nervosa, whereas our study did not confirm this association." (PMID 37007871, 2023). "It sheds some light on the importance of BDNF as a member of the neurotrophin family of growth factors as an underlying attributable risk factor for eating disorders." (PMID 35850718, 2022). "Since polymorphisms in the BDNF gene have been associated to higher probability of developing eating disorders, the role of BDNF in vulnerability to ABA has attracted interest." (PMID 34600568, 2021). "The low level of circulatory BDNF is associated with a higher risk of eating disorder including anorexia nervosa and bulimia nervosa." (PMID 32272767, 2020). "A high level of circulating BDNF has been linked to a healthy lifestyle and a low level of BDNF has been associated with metabolic risk factors and eating disorders." (PMID 31781387, 2019). "Several studies have found an association between the Val66Met (G196A) polymorphism of the Brain-Derived Neurotrophic Factor (BDNF) and Eating disorders." (PMID 20573217, 2010). "The aim of this study was to determine the association of the Val66Met (G196A) polymorphism of the BDNF gene and its effect on eating disorders (ED), energy intake and BMI in schoolchildren." (PMID 20573217, 2010). "Our data now raise the distinct possibility that eating disorders such as anorexia nervosa may be caused in part by the “sub-normal” levels of circulating BDNF and the resultant failure to activate the peripherally accessible orexigenic TrkB axis." (PMID 18382675, 2008). "This hypothesis is mirrored by studies investigating peripheral BDNF levels in eating disorders that provide evidence that higher BDNF levels in eating disorders might represent an illness-associated and acquired resistance to BDNF with respect to its anorexigenic properties." (PMID 33367955, 2021). "In recent decades, its intricate involvement has extended to eating disorders, with compelling evidence linking BDNF to several disorders including anorexia nervosa (AN)." (PMID 39203753, 2024). "Systematic reviews and meta-analyses have found positive correlations between decreased circulating BDNF levels and disordered eating and other psychiatric conditions." (PMID 35850718, 2022). "It is the first meta-analysis comparing the level of BDNF in individuals across the eating disorder spectrum to healthy controls." (PMID 35850718, 2022). "The purpose of this study is to determine if serum or plasma levels of BDNF are altered in individuals with eating disorders (EDs) compared to controls." (PMID 35850718, 2022). "Three studies out of nine showed statistically significant growth of BDNF levels after psychotherapy; two of the studies investigated patients with eating disorders treated with a behavioral program with elements of cognitive therapy." (PMID 34640441, 2021). "BDNF rs7124442 SNP has been shown to be functionally related to BDNF plasma levels in subjects with eating disorders." (PMID 32859253, 2020). "BDNF levels have been intensively studied in eating disorders, mostly in small groups of adult patients." (PMID 32184739, 2019). "For instance, one study indicated that eating disorders may be linked to serotonin receptor (5-HT2AR) and brain-derived neurotrophic factor (BDNF) genes." (PMID 40771647, 2025).
eating disorder (continued). "Except for four studies, all the other included ones reported a negative association between the level of BDNF and the presence of any type of eating disorders, meaning the levels of BDNF was lower among ED individuals compared to healthy controls." (PMID 35850718, 2022). "BDNF levels correlate with the severity of eating disorder symptomatology and, thus, could be related to aberrant eating behaviors occurring in AN." (PMID 32184739, 2019). "However, the values of BDNF concentration in blood plasma depend on many factors, among others mental illness, eating disorders, lower respiratory tract infections, and physical activity." (PMID 31284593, 2019). "The only significant associations identified were to eating disorders and high plasma BDNF levels as well as a significant negative influence of TT genotype on treatment response to SSRI, opposed to CC." (PMID 22087305, 2011). "Similarly, low levels of serum BDNF were reported in patients with metabolic and eating disorders." (PMID 34833132, 2021). "The rs7124442T/rs11030102C/rs11030119G haplotype in the BDNF gene was associated with higher BDNF plasma levels, albeit in eating disorder patients while a similar but non-significant trend was observed in control group consisting of sibling pairs discordant for the disorder." (PMID 22523577, 2012). "Regarding BDNF, a neurotrophin responsible for synaptic plasticity as well as the development, function and survival of neurons, this growth factor is generally hypothesized to play an important role in several neuropsychiatric conditions, including other eating disorders." (PMID 33572701, 2021). "Thus, while differences in nucleotide sequence between AN and controls may not differ significantly, it is possible that gene expression or methylation patterns, perhaps in BDNF SNP rs6265, may significantly vary in those with eating disorders in relation to measures of WM capacity." (PMID 29018381, 2017). "Statistically significant negative correlations between BDNF and the severity of eating disorders symptoms were found." (PMID 32184739, 2019). "Given the effect of BDNF on regulating eating behavior and body weight and the effect of dietary restrictions on BDNF and the gut microbiome, the TRF diet could possibly be a new way to successfully manage weight through modifying BDNF in people with eating disorders, including food addiction." (PMID 35689257, 2022).